CXCL11 (C-X-C motif chemokine ligand 11)
Diseases named in the same sentence as CXCL11 in open-access papers (continued):
Sharing a sentence is not in itself a finding about the gene and the disease.
colon carcinoma (36 papers, 2009 to 2025). "For example, researchers have found that CXCL11 is highly expressed in colon cancer, which is associated with prolonged survival." (PMID 40520002, 2025). "Colon cancer cells with high RBP‐Jκ expression induced the expression of TGF‐β1 in tumour‐associated macrophages by secreting CXCL11." (PMID 34655278, 2021). "Moreover, the IL6/JAK/STAT3 pathway has been found to upregulate CXCL1, CXCL2, CXCL3, and CXCL11 in patients with colon cancer, which was associated with prognosis." (PMID 35468892, 2022). "Interestingly, CXCL11, encoding the chemokine ligand C-X-C motif chemokine ligand 11, has been reported to be significantly upregulated in colon cancer tissues and to be associated with a better prognosis." (PMID 35473611, 2022). "Moreover, CXCL11 expression allowed risk-stratification even in the clinically relevant subgroup of locally restricted colon cancer (UICC/AJCC stage II, n=71)." (PMID 29163806, 2017). "Similarly, CXCL11 has been linked to migration and metastasis promotion in hepatocellular carcinoma, while also showing immune-related and better prognostic implications in colon cancer." (PMID 37777759, 2023). "Many tumour cell genes exhibit expression and functional characteristics, such as CXCL11, which is highly expressed in colon cancer and is correlated with anti-tumour immunity and improved prognosis." (PMID 41162582, 2025). "In colon cancer, RFX1 expression was mainly negatively correlated with chemokine-associated immunokines, such as CXCL10 and CXCL11." (PMID 41425715, 2025). "This highlights the significance of the interplay between RBP-Jκ and CXCL11 in the context of colon cancer cells and TAMs." (PMID 38791448, 2024). "Research has shown that the chemokine ligand C-X-C motif chemokine ligand 11 (CXCL11), also an oncogene, correlates with an improved prognosis in colon cancer." (PMID 37828426, 2023). "Data from The Cancer Genome Atlas (TCGA) and Gene Expression Omnibus (GEO) show that CXCL11 expression is upregulated in colon cancer tissue compared with healthy tissue, and that a high level of CXCL11 is correlated with prolonged survival." (PMID 33777950, 2021). "Using an RNA sequencing assay, we found that RBP‐Jκ was able to upregulate the expression of CXCL11 in colon cancer cells." (PMID 34655278, 2021). "Our research revealed that colon cancer cells secreted CXCL11 via overexpression of RBP‐Jκ to enhance the expression of TGF‐β1 in tumour‐associated macrophages to further promote metastasis of colon cancer cells." (PMID 34655278, 2021). "It has also been reported that the expression of CXCL9, CXCL10, and CXCL11 is upregulated in the tumor tissues of patients with colon cancer, esophageal cancer, lung cancer, and ovarian cancer, and correlates with better clinical outcomes." (PMID 34885241, 2021). "CXCL11 promotes tumor cell proliferation and invasion by inducing macrophage infiltration, which leads to poor prognosis of colon cancer." (PMID 33401247, 2020). "CXCL1, CXCL2, CXCL3, and CXCL11 were upregulated in patients with colon cancer and significantly correlated with prognosis." (PMID 32337262, 2020). "Initial quantitative PCR studies of ex vivo tissue specimen showed that CXCL9, CXCL10 and CXCL11 are significantly increased in human colon tumors compared to unaffected tissue." (PMID 29671006, 2018). "In accordance, tissue explants from colon carcinoma with above-threshold CXCL11 mRNA expression showed constitutive secretion of CXCL11, significantly increased compared to normal tissue." (PMID 29163806, 2017). "In accordance, all colon cancer cell lines tested secreted CXCL11 after stimulation with pro-inflammatory cytokines." (PMID 29163806, 2017). "CXCL9 and CXCL10 were identified as T-cell homing factors in colon cancer, and increased CXCL11 expression is a marker for less aggressive disease." (PMID 29163806, 2017).
colon carcinoma (continued). "Furthermore, qRT-PCR experimental results further confirmed that compared with normal colon epithelial cells, the expression levels of CCL22, CXCL1, CXCL8, and CXCL11 were upregulated in colon cancer cells." (PMID 38791448, 2024). "Levels of CXCL11 correlates with antitumor immunity and an improved prognosis in colon cancer." (PMID 38053658, 2023). "Intriguingly, one recent study identified that one single immune-related gene, CXCL11, could be an effective independent prognostic biomarker for colon cancer patients and upregulation of CXCL11 expression was correlated with a PD-L1 high expression level." (PMID 35600382, 2022). "However, there have also been reports of CXCL9, CXCL10, and CXCL11 that promote tumor proliferation in colon cancer, esophageal adenocarcinoma, and head and neck cancer by promoting inflammation or other mechanisms." (PMID 32685487, 2020). "Our results establish intratumoral CXCL11 as promising prognostic parameter for colon cancer." (PMID 29163806, 2017). "The association of CXCL11 with cancers has not been studied, and several research studies about the role of CXCL11 in tumors have been limited to only specific types of cancer such as colon cancer." (PMID 35935945, 2022). "Overexpression of S100A8/S100A9 in mouse colon cancer cells CT26.WT led to differential increases in the secretion levels of various cytokines (CXCL5, CXCL11, GM-CSF, G-CSF, IL1a, IL1b, sTNF RI, and CCL3)." (PMID 38817853, 2024). "Our results showed that CXCL1, CXCL2, CXCL3, and CXCL11 were all upregulated in colon cancer compared with healthy tissues, and in the colon cancer group, a high level of CXCL1, CXCL2, CXCL3, and CXCL11 was correlated with better survival in TCGA or GEO." (PMID 32337262, 2020). "In accordance, migration of patient-derived cytotoxic T-cells towards autologous colon cancer cells has been shown to be mediated by CXCR3 expressed on T-cells, and by CXCL11 expressed by tumor cells." (PMID 29163806, 2017). "We previously identified chemokines CXCL9, CXCL10, and CXCL11, as well as GZMB (Granzyme B), as part of a prognostic gene signature in colon cancer." (PMID 29163806, 2017). "The expression of CXCR3 receptors by human and murine colon carcinoma cells has led us to determine the ability of the corresponding ligands (mouse CXCL9, CXCL10 and CXCL11) to induce their migration in vitro." (PMID 19436305, 2009). "Additionally, in colon cancer cells, the overexpression of RBP-Jκ leads to the secretion of CXCL11, which, in turn, promotes cancer cell migration induced by tumor-associated macrophages (TAMs) through TGF-β1 secretion." (PMID 38791448, 2024). "However, CXCL11 has been included in the TME immune score algorithm and widely investigated in various cancers, including colon cancer." (PMID 36330510, 2022). "In experimental models of colon cancer, local exposure to CXCL11 stimulates tumor growth, without affecting tumor angiogenesis in vivo, but no information is available for RCC models." (PMID 34200459, 2021). "Similarly, 11 genes were differentially expressed in colon cancer (CXCL1, 2, 3, 5, 8, 9, 10, and 11 were up-regulated, and CXCL11, 12, 13, and 14 were downregulated)." (PMID 34439306, 2021). "Interestingly, in our research, we found that in colon cancer cells, RBP‐Jκ‐induced CXCL11 was able to enhance the function of TAMs." (PMID 34655278, 2021). "Along that line, high expression of CXCL9 and CXCL10, but not CXCL11, was associated with the attraction of memory CD8 T-cells with a specific TCR repertoire in colon cancer, indicative of good prognosis." (PMID 29163806, 2017). "Notably, SPINK1 and CXCL11 gene copy numbers exhibited a positive correlation with gene mRNA levels, while MAFB copy number displayed a negative correlation with its gene mRNA level in colon cancer tissues." (PMID 38577604, 2024).
ovarian carcinoma (25 papers, 2009 to 2025). A malignant neoplasm originating from the surface ovarian epithelium. "As measured by RT‐qPCR, olaparib treatment caused significant upregulation of CXCL11 mRNA expression in multiple ovarian cancer cell lines." (PMID 34047476, 2021). "Furthermore, high levels of CXCL11 expressed in cancer-associated fibroblasts in ovarian cancer biopsies were found to facilitate cancer cell metastasis." (PMID 36969851, 2023). "High expression of CXCL2, CXCL10, and CXCL11 is correlated with favorable prognoses in ovarian cancer." (PMID 40689422, 2025). "We have previously reported that ovarian cancer patients with platinum-refractory disease, who were treated with IP IL-2 and responded favorably, had markedly increased eosinophils and serum CXCL11/eotaxin at the completion of treatment." (PMID 40642792, 2025). "R54 prevented the mesenchymal transition increasing E-CADHERIN and attenuating the mesenchymal markers expression.To evaluate the role of CXCR7 in EMT, CXCL11 mediated EMT genes expression was analysed in ovarian cancer cells plus R54." (PMID 39700131, 2024). "Our results align with these findings and show that CXCL1, CXCL5, CXCL8, and CXCL11 are overexpressed in ovarian cancer." (PMID 36969851, 2023). "Previously, a decrease in CXCL11 gene expression was observed in macrophages co-cultured with ovarian cancer cells." (PMID 37445941, 2023). "Increased levels of the chemokines CXCL9, CXCL10, CXCL11, and CCL5 are all associated with an immune-reactive ovarian cancer microenvironment and improved patient prognosis." (PMID 35131874, 2022). "To further validate that genomic instability ovarian cancer cells activate the CXCL11 expression signature, we conducted in vitro experiments." (PMID 34047476, 2021). "CXCL11- mediated migration reflects CXCR7 expression in ovarian cancer cell lines." (PMID 39700131, 2024). "Thus, we also examined CXCL9, CXCL10, CXCL11 in the ovarian cancer cell lines, ES2 and SKOV3, that overexpress ISG20, and found that CXCL10 and CXCL11 were significantly upregulated." (PMID 37342328, 2023). "Finally, in vivo and in vitro experiments confirmed that olaparib could upregulate the expression of CXCL11 in ovarian cancer cell lines." (PMID 34047476, 2021). "Both CXCL10 and CXCL11 mediate CD8+ T-cell responses, and CXCL10 promotes C8+ T-cell activation in ovarian cancer." (PMID 40689422, 2025). "CXCL11 is highly expressed in the immunoreactive subtype, and its ligand CXCL11 and receptor CXCR3 characterize this subtype, with the CXCL11-CXCR3 signaling pathway being a therapeutic target for ovarian cancer." (PMID 39680618, 2024). "Univariate Cox analysis demonstrated that CXCL9, CXCL10, CXCL11, and CXCL13 were protective factors in ovarian cancer (HR < 1, p < 0.01)." (PMID 38054797, 2023). "In vivo experiments showed that compound 968 increased the infiltration of CD3+ T cells into ovarian cancer and enhanced the secretion of CXCL10 and CXCL11 by ovarian cancer cells." (PMID 36523985, 2022). "Our results showed that CXCL1, CXCL8, CXCL9, CXCL11, CXCL12, CXCL16, and CXCL17 were remarkably elevated in ovarian cancer compared to those in normal tissue." (PMID 33763130, 2021). "We found that the coexpression of CXCL11 and ICB‐related genes was not only present in ovarian cancer, but also in 32 other cancer types." (PMID 34047476, 2021). "The transcriptional levels of CXCL1, CXCL8, CXCL10, CXCL11, CXCL12, CXCL13, and CXCL14 were significantly elevated while CXCL3 was obviously reduced in ovarian cancer vs normal ovarian tissue." (PMID 33763130, 2021). "Using ERα‐positive TOV2295 and TOV3133G cells generated from human ovarian carcinomas, we also found a similar expression profile with the upregulation of CXCR7 and CXCL11 in response to estrogen, which further validates the distinct regulation in OC cells." (PMID 30051594, 2018).
ovarian carcinoma (continued). "Ovarian cancer cell-derived lymphotoxin up-regulates CXCL11 secretion by CAFs; CXCL11, on the other hand, activates chemokine receptor CXCR3 on ovarian cancer cells and promotes their proliferation and motility." (PMID 26751490, 2016). "In ovarian cancer, all of the up-regulated genes were increased with more advanced stage (CXCL10, RIPK2 and SPP1) or higher pathological grade (CXCL11, KPNA2, RSAD2, THOC4 and TNC)." (PMID 23536776, 2013). "The third CXCR3-A ligand CXCL11 had been shown before not to be present in ovarian cancer ascites in detectable amounts." (PMID 28504691, 2017).
colorectal cancer (22 papers, 2016 to 2025). A primary or metastatic malignant neoplasm that affects the colon or rectum. "It has been shown in colorectal cancer that decreased CXCL11 levels were associated with an inhibition of cancer cell growth and epithelial-mesenchymal transition." (PMID 38609887, 2024). "Neuroendocrine-like cell-derived CXCL10 and CXCL11 induce the infiltration of tumor-associated macrophages and lead to the poor prognosis of colorectal cancer." (PMID 32337262, 2020). "In addition, six homeostatic chemokines, CXCL12, CCL1, CCL20, CCL25, CCL27, and CXCL11, were upregulated in the peripheral blood of patients with advanced colorectal cancer, which has also been reported to be associated with tumor progression." (PMID 37063892, 2023). "Furthermore, hypoxia was found to increase CXCL11 expression in macrophages associated with colorectal cancer (CD68+ cells)." (PMID 32121394, 2020). "For instance, a study on colorectal cancer (CRC) reported that CXCL11 gene expression is upregulated in colon adenocarcinoma (COAD) tissues." (PMID 41357585, 2025). "The chemokine ligand C-X-C motif chemokine ligand 11 (CXCL11) is involved in the progression of various cancers, but its biological roles in colorectal cancer (CRC) remain confused." (PMID 33777950, 2021). "In colorectal cancer tissues, western blot analyses revealed that CXCL11 expression, known to be the ligand of CXCR3, was enhanced compared to normal tissues." (PMID 32121394, 2020). "Downregulation of CXCL11 inhibits colorectal cancer cell growth and epithelial-mesenchymal transition." (PMID 32337262, 2020). "All colorectal cancer cell lines tested produced CXCL11 after stimulation with the cytokines IFNγ and TNFα, as evidenced by qRT-PCR and by ELISA." (PMID 29163806, 2017). "Our finding showed that CXCL10 and CXCL11 play important roles in the interaction of neuroendocrine differentiation and TAMs and the poor prognosis of colorectal cancer." (PMID 27034164, 2016). "A similar result for CXCL11 was also illustrated in colorectal cancer." (PMID 35281472, 2022). "Similarly, high expression of CXCL11 in a colorectal cancer model was shown to recruit CXCR3+ Tregs." (PMID 30319622, 2018). "Therefore, we evaluated the contribution of the CXCR3-ligands CXCL9, CXCL10 and CXCL11 to colorectal carcinogenesis by analysis of their expression and prognostic relevance in human colorectal cancer tissue." (PMID 29163806, 2017). "For example, in colorectal cancer tissue, CXCL1, CXCL2, CXCL3, CXCL5, CXCL8, and CXCL11 were highly expressed, while CXCL12, CXCL13, and CXCL14 were little expressed." (PMID 36612163, 2022). "Specifically, miR-144 was down-regulated in colorectal cancer cells and tissues, and suppressed cancer development by directly targeting SMAD4 and CXCL11." (PMID 32351538, 2020). "CXCL9, CXCL10, CXCL11/CXCR3 axis has been proved to regulate immune cell migration, differentiation, and activation, leading to tumor suppression in pancreatic adenocarcinoma, colorectal cancer and so on." (PMID 34777466, 2021). "However, studies also indicated that CXCL11 played important roles in promoting the chemotaxis activity of TAM, which was related to the poor prognosis of colorectal cancer." (PMID 31781593, 2019). "Cancer-associated fibroblasts (CAF) derived from colorectal cancer, as well as monocyte-derived THP1 cells showed inducible CXCL11 expression on mRNA, but not on protein level." (PMID 29163806, 2017). "It has been reported that L-OHP also can upregulate the expression of HMGB1 in colorectal cancer cells, but our results show that L-OHP neither upregulated the expression of CXCL11 nor stimulated the release of HMGB1 in A549 and H460 cells." (PMID 30744691, 2019).
autoimmune disease (20 papers, 2014 to 2025). A disorder resulting from loss of function or tissue destruction of an organ or multiple organs, arising from humoral or cellular immune responses of the individual to their own tissue constituents. "Increased serum levels of TNFSF13B protein have previously been found in autoimmune diseases, and CXCL11 has also been implicated in autoimmune diseases." (PMID 25298177, 2014). "Additionally, rs6816425 is a strong cis-eQTL for increased expression of CXCL11 in the pancreas, which has been implicated in autoimmune disease pathogenesis, including diabetes, and is associated with insulin resistance in obese individuals." (PMID 39530122, 2024). "Moreover, recent reviews suggested that the chemokines, CXCL10, CXCL9, and CXCL11, are implicated in the pathogenesis of autoimmune diseases such as autoimmune thyroiditis, T1DM, Graves disease, Thyroid eye disease, and Addison’s disease." (PMID 35242125, 2021). "Moreover, recent reviews suggested that chemokines, CXCL10, CXCL9, and CXCL11, are implicated in the pathogenesis of autoimmune diseases such as autoimmune thyroiditis, type 1 diabetes, Graves disease, Thyroid eye disease, and Addison’s disease." (PMID 34054797, 2021). "But given its role in other autoimmune diseases and the relationship with CXCL9 and CXCL10, we also included CXCL11 in our study as a potential pathogenic factor." (PMID 39981245, 2025). "This suggests that CXCL10 and CXCL11 are indicators of disease progression, warranting further investigation into their roles in autoimmune disorders beyond pSS." (PMID 38900301, 2024). "Studies have shown that CXCL9, CXCI 10, and CXCL11 are involved in the immune dysfunction of target organs and over-amplification of local inflammatory responses at lesion sites in many autoimmune diseases, including IBD." (PMID 36635421, 2023). "Elevated CXCL11 levels have also been observed in mixed cryoglobulinemia, Graves’ disease, and autoimmune diseases." (PMID 37493737, 2023). "There are limited in-vivo studies of CXCL11 functions, but studies have found elevated levels in patients with autoimmune disease and high levels of all three IFN-γ inducible chemokines have been associated with a poor prognosis in many types of cancers." (PMID 35709177, 2022). "Studies have also suggested associations between the disease activity of autoimmune diseases and serum or BALF CXCL9, CXCL10, and CXCL11 levels in patients with SLE, DM, or SScs." (PMID 33137121, 2020). "The increased expression of CXCL9 and CXCL11 may also excessively activate the hippocampal type Th1 immune and inflammatory response and trigger autoimmune diseases, but the upregulated expression of LYN (ratio: 2.06) eliminated our concerns." (PMID 31031647, 2019). "Among them, CXCR3 and its chemokines CXCL10, CXCL9, and CXCL11 are widely involved in the pathogenesis of autoimmune diseases such as HT, GD, thyroid eye disease (TED), type 1 diabetes, and autoimmune Addison’s disease, and may be potential targets for new drugs to treat these diseases." (PMID 35720300, 2022). "Here, we consider the genes CXCL11, CCL2 and APOBEC3A, as they are connected with autoimmune diseases, including systemic lupus erythematosus and thus potential therapeutic targets in the management of patients with lupus and, likely, other interferonopathies." (PMID 37770709, 2023). "In many autoimmune diseases, CXCL9 and CXCL11 are involved in the immune dysfunction in the target organs and excess amplification of the local inflammatory response in patients with various diseases." (PMID 31031647, 2019). "Some of these disrupted inflammatory mediators, like CXCL11, CXCL20, IL-6, IL-1β, are involved in the pathogenesis of autoimmune disorders and play a potential role in tumor progression and metastasis." (PMID 31200452, 2019).